APOB (apolipoprotein B)
Description:
Apolipoprotein B is a major protein constituent of chylomicrons (apo B-48), LDL (apo B-100) and VLDL (apo B-100). Apo B-100 functions as a recognition signal for the cellular binding and internalization of LDL particles by the apoB/E receptor.
Synonyms: ApoB-100; FCHL2; FLDB; LDLCQ4; apoB-48
Tractability: Small molecule: it belongs to a druggable protein family. Antibody: UniProt places it where antibodies can reach, with high confidence; its Gene Ontology location is reachable by antibodies, with high confidence; UniProt predicts a signal peptide or a membrane-spanning region. PROTAC: ubiquitination databases record sites on it; a small molecule that binds it is known.
Target class: Secreted protein
Safety:
Unwanted effects reported when the protein is acted on. In parentheses: how it was acted on, where the effect was seen, and who reports it.
Increased, Liver Steatosis (activation; blood; source: AOP-Wiki)
bleeding (source: ClinPGx)
bleeding at therapeutic INR (source: ClinPGx)
Gene: Protein-coding gene on chromosome 2 (21,001,429 to 21,044,073, reverse strand). Ensembl gene ENSG00000084674.
Subcellular location: Cytoplasm; Secreted; Lipid droplet
Subcellular location (Human Protein Atlas): Cytosol; Vesicles; Predicted to be secreted
Pathways (Reactome):
Transport of small molecules: Chylomicron assembly; Chylomicron clearance; Chylomicron remodeling; LDL clearance; LDL remodeling; VLDL assembly; VLDL clearance
Vesicle-mediated transport: Cargo recognition for clathrin-mediated endocytosis; Clathrin-mediated endocytosis; Scavenging by Class A Receptors; Scavenging by Class B Receptors; Scavenging by Class F Receptors; Scavenging by Class H Receptors
Hemostasis: Cell surface interactions at the vascular wall; Platelet sensitization by LDL
Metabolism of proteins: Post-translational protein phosphorylation; Regulation of Insulin-like Growth Factor (IGF) transport and uptake by Insulin-like Growth Factor Binding Proteins (IGFBPs)
Cellular responses to stimuli: Heme signaling
Immune System: Regulation of TLR by endogenous ligand
Sensory Perception: Retinoid metabolism and transport
Gene Ontology:
Molecular function: cholesterol transfer activity; heparin binding; lipase binding; low-density lipoprotein particle receptor binding; phospholipid binding; protein binding; receptor ligand activity; lipid transporter activity
Biological process: cellular response to lipoprotein particle stimulus; cholesterol homeostasis; cholesterol metabolic process; cholesterol transport; low-density lipoprotein particle clearance; low-density lipoprotein particle remodeling; positive regulation of cholesterol storage; positive regulation of lipid storage; positive regulation of macrophage derived foam cell differentiation; response to virus; very-low-density lipoprotein particle assembly; lipoprotein transport; triglyceride mobilization; lipid metabolic process; lipid transport; signal transduction
Cellular component: chylomicron; cytoplasm; cytosol; endoplasmic reticulum exit site; extracellular exosome; extracellular region; intermediate-density lipoprotein particle; lipid droplet; low-density lipoprotein particle; mature chylomicron; neuronal cell body; very-low-density lipoprotein particle; chylomicron remnant; clathrin-coated endocytic vesicle membrane; early endosome; endocytic vesicle lumen; endoplasmic reticulum lumen; endoplasmic reticulum membrane; endosome lumen; endosome membrane; intracellular membrane-bounded organelle; lysosomal lumen; plasma membrane; smooth endoplasmic reticulum; endoplasmic reticulum
Genetic constraint (gnomAD): Loss-of-function variants: 150 observed, 320.03 expected, observed/expected ratio (o/e) 0.47, 90% interval 0.41 to 0.54. The upper end of that interval is the gene's LOEUF score, 0.54, which puts it in group 2 of 6, group 1 being the genes least tolerant of losing a copy. Missense variants: 5,271 observed, 5,466.2 expected, observed/expected ratio (o/e) 0.96, 90% interval 0.94 to 0.99. Synonymous variants: 2,013 observed, 2,083.7 expected, observed/expected ratio (o/e) 0.97, 90% interval 0.93 to 1.
Gene-disease validity (ClinGen):
ClinGen rates the evidence that APOB causes each of these diseases.
familial hypobetalipoproteinemia 1 (semidominant): Definitive. Any hypobetalipoproteinemia in which the cause of the disease is a mutation in the APOB gene.
hypercholesterolemia, autosomal dominant, type B (autosomal dominant): Definitive.
Homologues: Orthologues: chimpanzee APOB (99% identical), macaque APOB (94% identical), rabbit APOB (77% identical), pig APOB (76% identical), dog APOB (74% identical), guinea pig APOB (70% identical), mouse Apob (70% identical), rat Apob (69% identical), zebrafish apoba (32% identical), zebrafish apobb.1 (24% identical), zebrafish apobb.2 (16% identical).
Diseases named in the same sentence as APOB in open-access papers:
APOB is named in the same sentence as 473 diseases in open-access papers, as found by Europe PMC text mining. Sharing a sentence is not in itself a finding about the gene and the disease. The quoted sentences say what the papers report.
atherosclerosis (576 papers, 2007 to 2026). A disease characterized by the build-up of fatty material and calcium deposition in the arterial wall resulting in partial or complete occlusion of the arterial lumen. "Apolipoprotein B was also the only biomarker independently associated with left main atherosclerosis, also showing a strongest association with the Gensini score." (PMID 41374382, 2025). "The progression of atherosclerosis and its associated complications is primarily instigated by the infiltration of cholesterol-rich lipoproteins containing apolipoprotein B (apoB) into the subendothelial matrix, where they are retained." (PMID 41303445, 2025). "Several attempts have been made to inhibit hepatic apoB-Lp production to lower plasma lipids and atherosclerosis; however, these ventures have been associated with increased lipid storage in the liver." (PMID 39782688, 2025). "Elevated ApoB levels, representing LDL levels, are associated with the occurrence of CAD, and ApoB levels are positively correlated with the Gensini score, indicating the degree of atherosclerosis and arterial narrowing." (PMID 39851250, 2025). "Numerous clinical trials, as well as Mendelian randomization studies, have demonstrated a causal role of apolipoprotein B (apoB)-containing lipoproteins in the initiation of atherosclerosis." (PMID 41150735, 2025). "A further comprehensive study has demonstrated that higher levels of ApoB are significantly associated withresidual risk of coronary atherosclerotic heart disease and the severity ofcoronary atherosclerosis." (PMID 39867191, 2025). "Elevated levels of lipid ApoB have been implicated in atherosclerosis formation, thereby increasing the risk of CVD, and these reports were consistent with the results of our study." (PMID 40678973, 2025). "In this context, among other factors that serve as T cell‐activating antigens, LDL and its core protein apolipoprotein B show strong association with atherosclerosis." (PMID 39909868, 2025). "Through its role in cholesterol delivery to peripheral tissues, ApoB is closely associated with the pathogenesis of atherosclerosis and plaque formation." (PMID 41346943, 2025). "More than 100 ApoB-100 epitopes that are associated with an immune response in humans have been identified, and some have been shown to reduce atherosclerosis when used as part of a vaccination approach." (PMID 38397127, 2024). "Arterial stiffness is a major contributor to human aging, and abnormal ApoB levels increase atherosclerosis and cardiac load, potentially increasing the risk of CVD and death." (PMID 38789961, 2024). "The significance of apoA-I and apoB in ICAS can be explained in detail by their roles in atherosclerosis, the underlying pathology of ICAS." (PMID 38978811, 2024). "ApoB is a superior cardiovascular risk marker because it accounts for all lipoprotein particles that can cause atherosclerosis." (PMID 39539858, 2024). "The retention of apolipoprotein B (apoB)-containing lipoproteins within the arterial wall plays a major causal role in the initiation and progression of atherosclerosis." (PMID 39334349, 2024). "An in vivo studysought to assess the capability of promoting ApoB mRNA editing fordecreasing the risk of atherosclerosis." (PMID 39228490, 2024). "Increased plasma concentrations of ApoB have been shown to be a key risk factor for the development of atherosclerosis." (PMID 38390206, 2024). "As expected, genetic inhibition of PCSK9 was associated with lower levels of LDL-C and ApoB, less subclinical atherosclerosis, lower risk of MOVE, including ischaemic stroke, and directionally concordant effects on risk of FOVE and MCE." (PMID 38198221, 2024).
atherosclerosis (continued). "The authors put hamsters on a high-cholesterol/high-fat diet to assessthe association between APOC3 and atherosclerosis and observed reducedlevels of TG, total cholesterol, ApoB, and ApoE and enhancedlevels of HDL-C and ApoA1." (PMID 39228490, 2024). "A higher ApoB/ApoA1 ratio is associated with an increased risk of atherosclerosis and myocardial infarction, making it a valuable marker in the prediction and management of cardiovascular events." (PMID 39273041, 2024). "Subcutaneous infusion of apolipoprotein B100 (ApoB100) to ApoE−/− mice was associated with abrogated atherosclerosis development and progression of atherosclerosis, which also appeared to be CD4+CD25+ Treg-dependent." (PMID 39061983, 2024). "Expression of tissue restricted antigen associated with atherosclerosis, namely apolipoprotein A (ApoB), also declined in thymus with age." (PMID 39061983, 2024). "In contrast, apolipoprotein B (ApoB) is involved in the transport of cholesterol from liver cells to peripheral cells, increasing the risk of atherosclerosis and CVD as it promotes the deposition of cholesterol in the arteries." (PMID 39728125, 2024). "Atherosclerosis is a chronic inflammatory disease caused by the accumulation of lipoproteins, containing plasma apolipoprotein B (apoB) in specific regions of the arterial tree." (PMID 38930939, 2024). "Plasma cholesterol, LDL cholesterol, and certain apolipoproteins, particularly Apolipoprotein B (ApoB), show strong associations with clinically apparent atherosclerosis." (PMID 39364414, 2024). "Accordingly, with the progression of CHB disease, the risk of atherosclerosis can be lowered, and the ApoB/ApoA1 ratio can be down-regulated." (PMID 38744926, 2024). "Lp(a) is a complex LDL-like particle carrying oxidized phospholipids (OxPLs) with a disulfide bridge between apolipoprotein A and apolipoprotein B and has been associated with atherosclerosis." (PMID 38486246, 2024). "Multi-ethnic studies of atherosclerosis confirmed ApoB as an independent risk factor for atherosclerosis." (PMID 37375689, 2023). "Given that LDL cholesterol is a known risk factor for atherosclerosis and cardiovascular disease, ApoB serves as an important marker." (PMID 37763183, 2023). "In fact, minimizing oxidant stress would significantly reduce the trapping of Apolipoprotein B in the intima, mitigate the association between lipids and chronic inflammation and impair the pathogenesis of atherosclerosis." (PMID 36901696, 2023). "Increased Lp(a) and ApoB levels are associated with heightened atherosclerosis risk, a condition identified by the accrual of fatty plaques within the arteries." (PMID 37763183, 2023). "Internalization of lipoprotein-containing ApoB by macrophages promotes foam cell formation, a hallmark of the fatty streak phase of atherosclerosis." (PMID 38149053, 2023). "Observational studies have demonstrated that high levels of LDL, apolipoprotein B (apo B) and triglycerides increase the risk of atherosclerosis, whereas high levels of HDL and apolipoprotein A (apo A) are associated with a lower risk of atherosclerosis." (PMID 37974282, 2023). "The present study aimed to investigate the association between apolipoprotein B (Apo B) and classical features associated with clinical or subclinical atherosclerosis." (PMID 36769130, 2023). "In terms of potential mechanisms, Lp(a) and ApoB are involved in several pathways linked to atherosclerosis and coronary artery disease." (PMID 37763183, 2023). "Autoimmunity in atherosclerosis is a delicate balance of protective and pathogenic events that has been best established in T cellular immunity against ApoB." (PMID 35479271, 2022).
atherosclerosis (continued). "In particular, apolipoprotein B (apoB)-containing lipoproteins have been shown to associate with atherosclerosis." (PMID 35371605, 2022). "Excessive concentrations of apolipoprotein B in plasma are risk factors for various cardiovascular and metabolic diseases, such as obesity, diabetes, and atherosclerosis." (PMID 36470666, 2022). "ApoA1 and apoB were the two major sources of apolipoproteins involved in lipid transport and were proven to function in the procession causing atherosclerosis and its complications." (PMID 36713523, 2022). "Per se, the generation of ApoB-autoantibodies represents an event of late-stage atherosclerosis, in which pathogenic T cell phenotypes and effector functions dominate protective limbs of autoimmunity." (PMID 35479271, 2022). "One of these genes, APOB, encodes for apolipoprotein B which is the primary apolipoprotein in the low-density lipoprotein cholesterol and is associated with atherosclerosis." (PMID 36506940, 2022). "This is because LDL-C concentrations approximate total LDL particle concentration, or number of apolipoprotein B (apoB) particles, which can enter the arterial intima and cause atherosclerosis." (PMID 36558530, 2022). "Here, we aimed to establish a clinical association between circulating human ApoB auto-antibodies with atherosclerosis and its clinical risk factors using a novel assay to detect auto-antibodies against a pool of highly immunogenic ApoB-peptides." (PMID 35479271, 2022). "Preventing and halting atherosclerosis requires eliminating apoB and its associated LDL-C from getting trapped in the intima." (PMID 36439997, 2022). "ApoB is an important risk factor for atherosclerosis and MI because of its association with atherogenic lipid profiles including LDL-C, VLDL and chylomicron remnants." (PMID 35317787, 2022). "Apolipoprotein B (APOB) is associated with the development of atherosclerosis and consequently in the acute coronary syndrome (ACS) physiopathology." (PMID 35440891, 2022). "One avenue that merits exploration is apolipoprotein B (apoB) and its prominent position as a causal factor in atherosclerosis." (PMID 34677405, 2021). "The Cardiovascular Risk in Young Finns Study shows that elevated ApoB and ApoB:ApoA1 ratio and reduced ApoA1 in children and adolescents reflects a predisposition to subclinical atherosclerosis in adulthood in healthy individuals." (PMID 33640328, 2021). "Of all proposed atherosclerosis-related (auto-) antigens, LDL-C and ApoB provide the strongest causal link between autoimmunity and the pathogenesis of atherosclerosis." (PMID 33669769, 2021). "PH is characterized by elevated plasma levels of cholesterol–specifically, LDL and apoB–which contribute to the development of atherosclerosis and associated ischemic events." (PMID 33959024, 2021). "Atherosclerosis is initiated by risk factor- and flow-induced endothelial damage, which predisposes for focal retention of apolipoprotein B (apoB)-containing lipoproteins in the arterial intima." (PMID 35087883, 2021). "ApoB and apoA1 are major apolipoproteins involved in lipid transport and the pathogenic processes and complications of atherosclerosis." (PMID 33774330, 2021). "It is important to note that CD4+ T-cells in patients with a high ApoB:ApoA1 ratio showed increased response to oxidative stress signalling, a process that has been implicated in atherosclerosis through oxidization of LDL and altered inflammatory processes." (PMID 33640328, 2021). "Increased levels of ApoB is positively associated with dyslipidemia and metabolic syndrome (MetS) and is an important risk factor for atherosclerosis and CVD." (PMID 32386512, 2020). "Further study should be conducted to evaluate the value of ApoB levels in the cord blood samples of growth restricted fetuses to identify risk of long-term atherosclerosis." (PMID 32000699, 2020).